PANK1 (pantothenate kinase 1)
Description:
[Isoform 1]: Catalyzes the phosphorylation of pantothenate to generate 4'-phosphopantothenate in the first and rate-determining step of coenzyme A (CoA) synthesis.
Synonyms: PANK; MGC24596; PANK1a; PANK1b
Tractability: Small molecule: a structure with a bound ligand is known; a high-quality ligand is known; it has a high-quality binding pocket. PROTAC: ubiquitination databases record sites on it; a small molecule that binds it is known.
Target class: Enzyme; Transferase
Chemical probes: PZ2891 (high quality)
Gene: Protein-coding gene on chromosome 10 (89,579,497 to 89,645,242, reverse strand). Ensembl gene ENSG00000152782.
Subcellular location: Cytoplasm; Nucleus (Isoform 1); Nucleus, nucleolus; Cytoplasm, cytosol (Isoform 2); Cytoplasmic vesicle, clathrin-coated vesicle; Recycling endosome
Pathways (Reactome):
Metabolism: Coenzyme A biosynthesis
Gene Ontology:
Molecular function: acetyl-CoA binding; pantothenate kinase activity; protein homodimerization activity; ATP binding
Biological process: coenzyme A biosynthetic process
Cellular component: cytoplasm; nucleus; recycling endosome; cytosol; clathrin-coated vesicle; nucleolus
Genetic constraint (gnomAD): Loss-of-function variants: 15 observed, 28.32 expected, observed/expected ratio (o/e) 0.53, 90% interval 0.35 to 0.82. The upper end of that interval is the gene's LOEUF score, 0.82, which puts it in group 3 of 6, group 1 being the genes least tolerant of losing a copy. Missense variants: 412 observed, 505 expected, observed/expected ratio (o/e) 0.82, 90% interval 0.75 to 0.88. Synonymous variants: 214 observed, 196.43 expected, observed/expected ratio (o/e) 1.09, 90% interval 0.97 to 1.22.
Homologues: Orthologues: chimpanzee PANK1 (99% identical), macaque PANK1 (99% identical), rabbit PANK1 (95% identical), dog PANK1 (95% identical), pig PANK1 (94% identical), guinea pig PANK1 (93% identical), rat Pank1 (92% identical), mouse Pank1 (91% identical), zebrafish pank1b (76% identical), tropical clawed frog pank1 (75% identical), zebrafish pank1a (70% identical), Drosophila melanogaster fbl (54% identical). Paralogues in human: PANK2 (68% identical), PANK3 (63% identical), PANK4 (29% identical).